IDH2 (isocitrate dehydrogenase (NADP(+)) 2)
Diseases named in the same sentence as IDH2 in open-access papers (continued):
Sharing a sentence is not in itself a finding about the gene and the disease.
astrocytomas (continued). "Of note, we found that CDK4/6 inhibitor selectively suppressed cell viability of phospho-Rb-upregulated, recurrent cells, further supporting the critical role of cell cycle deregulation in progression in IDH2-mutant astrocytoma." (PMID 38012788, 2023). "Together with the clinical characteristics and xenograft model, we found that CNAs involving RB pathway and PDGFRA promote tumor progression in astrocytoma, IDH2-mutant." (PMID 38012788, 2023). "Altogether, this study demonstrated the pivotal biological role of gene alterations that activate RB pathway and PDGFR pathway in the progression of IDH2-mutant astrocytoma." (PMID 38012788, 2023). "Here, we report a unique case of IDH2 mutant astrocytoma, CNS WHO grade 3 that developed tumor progression." (PMID 38012788, 2023). "Here we describe a case of a patient with an IDH-mutant astrocytoma, in which both IDH1 and IDH2 mutations were detected within the same tumour." (PMID 36286062, 2022). "Within a histologic grade, IV astrocytoma cohorts, akin to lower-grade astrocytomas, a mutation in IDH1 or IDH2 carries the most significant prognostic value." (PMID 32640746, 2020). "We present a case of IDH-mutant astrocytoma with a somewhat atypical molecular presentation, including a previously uncharacterized IDH2 mutation, retained ATRX expression, and lack of MGMT promoter hypermethylation." (PMID 41736408, 2026). "Notably, vorasidenib is now approved for the treatment of Grade II IDH1- or IDH2-mutant astrocytomas, marking a significant advancement in targeted therapy." (PMID 40223032, 2025). "Thus, mutations in the isocitrate dehydrogenase genes IDH1 and IDH2 define specific entities, associated with lower histologic grades and better prognosis when compared to IDH-wild-type astrocytomas." (PMID 41373636, 2025). "IDH-mutant astrocytomas are diffuse gliomas that are defined by characteristic mutations in IDH1 or IDH2 and do not have complete 1p/19q co-deletion." (PMID 39899075, 2025). "The fifth edition of the World Health Organization Classification of Tumors of the Central Nervous System requires identifying IDH1 or IDH2 mutation without 1p19q co-deletion for diagnosing an astrocytoma." (PMID 39906460, 2025). "However, as the drug exposure was short-term, further study is needed to address if prolonged use of mutant specific IDH2 inhibitor can induce anti-tumor effects in IDH2 mutant high-grade astrocytoma." (PMID 38012788, 2023). "However, the use of the anti-IDH1 R132H antibody has its limitations; although most oligodendrogliomas and low-grade astrocytomas carry the IDH1 R132H mutation, other mutations occur in IDH1 or IDH2 genes that cannot be detected with the antibody." (PMID 37568909, 2023). "Thus, this case is particularly unique and useful for better understanding molecular mechanisms of tumor progression in IDH2-mutant astrocytoma." (PMID 38012788, 2023). "However, the molecular mechanisms of malignant progression are poorly understood in IDH2-mutant astrocytoma." (PMID 38012788, 2023). "These clinical and preclinical findings support the role of PDGFRA gene alterations and downstream multiple signaling pathways, including PI3K/AKT/mTOR pathway and RAS/RAF/MEK/ERK pathway, in promoting progression of not only IDH1-mutant, but also IDH2-mutant astrocytoma." (PMID 38012788, 2023). "IDH mutated astrocytomas were rare, with one IDH1 and one IDH2 mutated tumor in our cohort." (PMID 34193285, 2021).
astrocytomas (continued). "Direct sequencing detected one IDH2 mutation in a grade II astrocytoma and additionally six IDH1 mutations were identified not attributed to R132H mutation or from samples with missing IDH1 immunohistochemistry." (PMID 28467778, 2017). "Also, our findings suggest that these genomic alterations may represent therapeutic targets in IDH2-mutant astrocytoma." (PMID 38012788, 2023). "Adult astrocytomas, particularly IDH1/IDH2-wildtype infiltrating astrocytic gliomas, represent a significant challenge for medical professionals." (PMID 41683621, 2026). "The gene set includes IDH1, IDH2, BRAF, CDKN2A/B, PTEN, and NOTCH1, but misses CIC, FUBP1, ATRX, and H3-3A important for oligodendroglioma and astrocytoma diagnosis." (PMID 37908227, 2023). "Similarly, it is possible that some cases classified as IDH-wild type (glioblastoma) should have been categorized as astrocytomas since only IDH-1 mutations were evaluated and IDH-2 mutations were not assessed." (PMID 39917141, 2025). "Also, not all ATRX mutations are associated with loss of nuclear staining, so in a tumor with classic astrocytoma histology and a confirmed IDH1 or IDH2 mutation, positive nuclear staining for ATRX does not exclude the diagnosis of astrocytoma." (PMID 30967140, 2019).
leukemia (77 papers, 2013 to 2025). A malignant (clonal) hematologic disorder, involving hematopoietic stem cells and characterized by the presence of primitive or atypical myeloid or lymphoid cells in the bone marrow and the blood. "Taken together, copper-associated therapeutics agents can be used to develop new strategies for targeting hematological malignancies, such as leukemia with IDH2 mutation." (PMID 40384935, 2025). "IDH2 mutation and copper are both involved in metabolic reprogramming, so we tried to establish leukemia cells carrying IDH2R140Q mutation for examining the potential effects under excess copper conditions." (PMID 40384935, 2025). "The abnormal splicing of INTS3 caused by the mutant SRSF2 binding to cis elements in INTS3 mRNA, along with the increased DNA methylation of INTS3 caused by the mutant IDH2, plays a role in the development of leukemia." (PMID 39034387, 2024). "So far ASXL1, SRSF2, IDH2 have been identified as unfavourable risk factors affecting overall (OS), leukemia-free (LFS), or myelofibrosis-free survival (MFFS) in PV." (PMID 36242602, 2023). "Numerous new emerging reports of exome sequencing have identified frequent mutations in the IDH1 enzyme or its homolog IDH2 in leukemia and other cancers." (PMID 35743098, 2022). "IDH1 and IDH2 mutations then cause a hypermethylation phenotype in leukaemia and inhibit haematopoietic stem cell differentiation." (PMID 34617422, 2022). "On the other hand, the IDH2 mutation is mostly required for leukemia cell proliferation and tumor growth." (PMID 34356864, 2021). "Another study has discovered cooperation of NPM1 and IDH2 mutations for leukemia development in mice through activation of the Hoxa9/Meis1 pathway, where NPMc and IDH2/R140Q increase the expression of Hoxa9 and Meis1, respectively." (PMID 34944812, 2021). "A study using a mouse model with combined mutation of TET2, FLT3-ITD, and IDH2-R140Q; thus, triple-transformed leukemia, showed tumor sensitivity both to 5-azacytidine and to IDH2 inhibitor enasidenib." (PMID 34947882, 2021). "Male IDH1 and IDH2 mutations and marrow blasts ≥5% were independent risk factors for worse leukemia free survival (LFS) (p < 0.05)." (PMID 33609081, 2021). "A fourth study was based on the development of leukemia through transformation of murine hematopoietic stem/progenitor cells with IDH2 mutants in cooperation with FLT3-ITD or NRAS mutant alleles." (PMID 32859092, 2020). "The successful development of effective targeted therapies for IDH1- and IDH2-mutant AMLs has led to the regulatory approval of IDH1 and IDH2 inhibitors, improving response rates and outcomes for patients whose leukemia harbors these mutations." (PMID 32859092, 2020). "In PV, ASXL1 and SRSF2 were associated with inferior OS, SRSF2 and IDH2 with shorter leukemia-free survival and SRSF2 with shorter myelofibrosis-free survival." (PMID 32781570, 2020). "The group of AMLs bearing IDH1 or IDH2 mutations is heterogeneous and a better definition of biologically and clinically relevant subgroups among these leukemias is very important to better define the spectrum of sensitivity to IDH-targeted therapies." (PMID 30813354, 2019). "Multiple studies have shown that IDH1/IDH2 mutations present in leukemia cause the accumulation of 2HG, inhibiting DNA demethylation and producing a hypermethylation phenotype." (PMID 29922517, 2018). "Similarly, IDH1 and IDH2 gain-of-function mutations in leukemia lead to the accumulation of the competitive inhibitor of TET enzymes, 2-hydroxyglutarate (2-HG), with consequent DNA hypermethylation." (PMID 41516186, 2025). "Ivosidenib and enasidenib specifically inhibit the activity of mutated IDH1 and IDH2 enzymes respectively to lower the 2-HG levels, which helps to restore the differentiation process of cells and reduces the malignant proliferation of leukemia cells." (PMID 39575391, 2024).
leukemia (continued). "Moreover, the same study observed that the mutation of the IDH2 gene represented an independent predictor of poor survival (p = 0.04) and a shorter duration of leukemia-free survival (p = 0.04)." (PMID 36982819, 2023). "However, IDH2 mutant (R140Q) AML cells surprisingly exhibited resistance to DM-αKG treatment, indicating a major difference between the leukemia cells with wt-IDH2 and those with mutated IDH2." (PMID 35313945, 2022). "Importantly, in this case report, two R/R AML patients with initial IDH1-R132C mutation achieved durable remissions with therapy of ivosidenib, but leukemia cells recurred with emergence of neomorphic mutation IDH2-R140Q." (PMID 35814406, 2022). "Moreover, single-cell sequencing analyses further demonstrated a polyclonal pattern was present at either MDS or AML stages, whereas IDH2 mutated cell clones appeared only at the leukemia stage." (PMID 36167633, 2022). "Mutations in IDH1 and IDH2 were recognized as independent factors for leukemia transformation." (PMID 33609081, 2021). "Mutations in IDH1 and IDH2 that result in a new enzymatic activity may represent novel, tractable targets for this genetically defined subset of leukemia patients." (PMID 23938080, 2013). "Moreover, after the combination of azacytidine with the IDH2 inhibitor AG-221, it can alleviate abnormal changes in DNA methylation, causing a decrease in the number of leukemia cells, which in turn is consistent with anti-leukemia activity to enhance sensitivity." (PMID 34001246, 2021). "After 48 h of excess copper (1 × 10−9∼1 × 10−7 M) treatment, a combination of copper and IDH2R140Q mutation robustly inhibited the viability of leukemia cells compared to wild type THP-1 and THP-1 with wild type IDH2 overexpression." (PMID 40384935, 2025). "Our previous studies identified several selective inhibitors of IDH2/R140Q that induce cellular differentiation in leukemia cells." (PMID 38347540, 2024). "Targeting IDH2/R140Q is the main strategy for the treatment of mutated AML and works by restoring leukemia cell differentiation." (PMID 38347540, 2024). "Significant association was also noted between SRSF2, IDH2, and RUNX1 for leukemia-free survival, and SRSF2 and RUNX1 for myelofibrosis-free survival." (PMID 37745842, 2023). "Our recent study showed that IDH2 enhanced the survival of colon cancer cells by promoting redox homeostasis and leukemia cells by promoting a reductive TCA cycle." (PMID 36831011, 2023). "More than 80% of patients with overt-PMF carry variants/mutations other than JAK2/CALR/MPL, in particular high-risk mutations which are associated with overall prognosis and leukemia-free survival (ASXL1, SRSF2, IDH1/IDH2, EZH2)." (PMID 36580136, 2023). "As such, a timely metabolic removal of α-KG by IDH2 would be critical for the leukemia cell survival." (PMID 35313945, 2022). "Since C-MYC is an important oncogene that plays a major role in leukemia cell survival and cancer metabolism, we thus used genetic and biochemical approaches to evaluate the potential link between IDH2 and c-Myc." (PMID 35313945, 2022). "An increased amount of d-2-hydroxyglutaric acid produced by IDH2-mutant leukemia cells directly contributes to cardiac insufficiency by inhibiting α-KGDH." (PMID 35755044, 2022). "We then used leukemia xenograft models to further evaluate the role of wt-IDH2 in AML proliferation in vivo." (PMID 35313945, 2022). "We showed that mitochondrial wild-type IDH2 plays a key role in this metabolic process and thus promotes leukemia cell survival and proliferation." (PMID 35313945, 2022). "To investigate the relevance of these findings in AML, we isolated primary leukemia cells from the peripheral blood of AML patients carrying wt-IDH2 or mutant IDH2 and treated the leukemia cells with DM-αKG." (PMID 35313945, 2022).
leukemia (continued). "The results showed that IDH2 knockdown significantly reduced tumor growth in both U937 and ML-1 leukemia models." (PMID 35313945, 2022). "To investigate the possible mechanisms by which wt-IDH2 promotes AML cell proliferation, we first tested the impact of IDH2 on the leukemia cell metabolism based on the enzymatic function of IDH2 in TCA cycle and mitochondrial metabolism." (PMID 35313945, 2022). "As such, the active reductive TCA cycle catalyzed by the highly expressed IDH2 in AML cells seems to play a major role in de novo synthesis of fatty acids essential for the proliferation of the leukemia cells." (PMID 35313945, 2022). "A closer look into the mutations that persisted following therapy (at remission) in responders revealed that they were in genes associated with pre‐leukaemia (ASXL1, DNMT3A, IDH2, SRSF2 and TET2)." (PMID 36051087, 2022). "The UBASH3A, SF3B1, RUNX1 and ASXL1 mutations gradually appeared and became the major clones at MDS stage, while IDH2 gradually emerged as the dominant clone at leukemia stage." (PMID 36167633, 2022). "The clonal evolution analysis of FA case (P1001) showed the mutations of UBASH3A, SF3B1, RUNX1 and ASXL1 gradually appeared at the later stage of MDS, while the IDH2 alteration become the dominant clone at the leukemia stage." (PMID 36167633, 2022). "AG‐221, a potent and specific inhibitor of mutant IDH2 that leads to the production of R‐2HG, has already shown significant survival benefits in aggressive leukemia." (PMID 33320958, 2021). "Despite the limitation of our sample size, this study has critically highlighted the prevalence of IDH1 and IDH2 in leukemia patients in the Saudi population." (PMID 34946913, 2021). "Despite parallel mechanisms of transformation, IDH1+ and IDH2+ leukemias show differences in both in vitro and clinical studies." (PMID 33976256, 2021). "IDH2 mutations cooperate with mutations in other genes such as Dnamt3a−/−, NPMc+, NrasG12D, and Flt3-ITD to induce leukemia in mice." (PMID 34944812, 2021). "IDH1 and IDH2-mutant mouse and human leukemia models suggest that they are sensitive to all-trans retinoic acid (ATRA) and the proapoptotic effect of arsenic trioxide (ATO) by themselves or in combination with each other." (PMID 34947882, 2021). "Other studies have supported a role of Meis1 and HoxA9 in cooperation with IDH1 or IDH2 mutant to drive leukemia development in mouse models." (PMID 32859092, 2020). "The ORR in patients with R/R IDH2-mutated AML was 40.3%, CR in 19.3%, and CRi in 6.8% (PR = 6.2%, morphological leukemia-free state = 8.0%)." (PMID 33335095, 2020). "By contrast, combined Flt3ITD and Tet2/Idh2-mutant leukemia was found to be maintained and propagated by the MPP lineage–restricted progenitor population." (PMID 29355841, 2018). "AG-221 was found to suppress 2-hydroxyglutarate (2-HG) levels in hematopoietic cells expressing mutant IDH2R140Q, and in murine models of IDH2-mutant leukemia." (PMID 28092669, 2017). "We obtained leukemia cell lines overexpressing wide-type IDH2 and IDH2R140Q." (PMID 40384935, 2025). "The overexpressed IDH-2 gene in AML promotes leukemia cell survival and proliferation in vitro as well as in vivo through active IDH-2-mediated conversion of alpha-ketoglutarate to isocitrate/citrate to facilitate glutamine utilization for fatty acid (FA) synthesis." (PMID 38071228, 2023).